LRRC41 (leucine rich repeat containing 41)
Description:
Probable substrate recognition component of an ECS (Elongin BC-CUL2/5-SOCS-box protein) E3 ubiquitin ligase complex which mediates the ubiquitination and subsequent proteasomal degradation of target proteins.
Synonyms: MUF1; PP7759
Tractability: PROTAC: ubiquitination databases record sites on it; its protein half-life has been measured.
Gene: Protein-coding gene on chromosome 1 (46,261,196 to 46,303,616, reverse strand). Ensembl gene ENSG00000132128.
Subcellular location (Human Protein Atlas): Nuclear bodies; Nucleoplasm
Pathways (Reactome):
Immune System: Antigen processing: Ubiquitination & Proteasome degradation
Metabolism of proteins: Neddylation
Signal Transduction: RHOBTB3 ATPase cycle
Gene Ontology:
Molecular function: protein binding; identical protein binding
Biological process: protein ubiquitination
Cellular component: membrane; cytoplasm; cytosol; nucleus
Genetic constraint (gnomAD): Loss-of-function variants: 17 observed, 64.9 expected, observed/expected ratio (o/e) 0.26, 90% interval 0.18 to 0.39. The upper end of that interval is the gene's LOEUF score, 0.39, which puts it in group 1 of 6, group 1 being the genes least tolerant of losing a copy. Missense variants: 745 observed, 1,026.5 expected, observed/expected ratio (o/e) 0.73, 90% interval 0.68 to 0.77. Synonymous variants: 416 observed, 423.63 expected, observed/expected ratio (o/e) 0.98, 90% interval 0.9 to 1.07.
Homologues: Orthologues: chimpanzee LRRC41 (100% identical), macaque LRRC41 (99% identical), rabbit LRRC41 (98% identical), dog LRRC41 (98% identical), pig LRRC41 (97% identical), guinea pig LRRC41 (97% identical), rat Lrrc41 (95% identical), mouse Lrrc41 (95% identical), tropical clawed frog lrrc41 (42% identical), zebrafish lrrc41 (21% identical).
Diseases named in the same sentence as LRRC41 in open-access papers:
LRRC41 is named in the same sentence as 5 diseases in open-access papers, as found by Europe PMC text mining. Sharing a sentence is not in itself a finding about the gene and the disease. The quoted sentences say what the papers report.
glioma (2 papers, 2021 to 2025). A benign or malignant brain and spinal cord tumor that arises from glial cells (astrocytes, oligodendrocytes, ependymal cells). "Therefore, although the role of UBA2 in glioma is corroborated by new empirical evidence, the role that LRRC41 plays in glioma is more hypothetical and should be further functionalized." (PMID 41300918, 2025). "Interestingly, some of these genes, e.g., LRRC41 and UBA2, have been identified previously as being related to tumor progression, cell cycle and ubiquitination pathways, and altered expression of these genes could be a cause of glioma pathogenesis." (PMID 41300918, 2025). "Conversely, there have not yet been direct functional studies of the involvement of LRRC41 in glioma; LRRC41 protein staining of glioma tissue is not detected on the Human Protein Atlas." (PMID 41300918, 2025).
hepatocellular carcinoma (2 papers, 2023 to 2025). A malignant tumor that arises from hepatocytes. "Nevertheless, LRRC41 has been involved in cancer pathways elsewhere (e.g., hepatocellular carcinoma), and one integrative multi-omics study has identified that LRRC41 is co-expressed with a block of genes that are negatively related to tumor phenotypes." (PMID 41300918, 2025). "In conclusion, our study revealed a significant upregulation of LRRC41 in hepatocellular carcinoma, suggesting its potential role in driving the clinicopathological progression of HCC." (PMID 38192337, 2023).
oligodendroglioma (2 papers, 2023 to 2024). A well-differentiated (WHO grade II), diffusely infiltrating neuroglial tumor, typically located in the cerebral hemispheres. "Both these blocks are negatively correlated with the group of genes GPBP1L1, LRRC41, CSDE1, FBXO42, and SFRS4, which are associated with the oligodendroglioma type." (PMID 38812741, 2024). "It was reported that LRRC41 could serve as a predictor of overall survival in patients with oligodendroglioma." (PMID 38192337, 2023).
cancer (4 papers, 2021 to 2025). A tumor composed of atypical neoplastic, often pleomorphic cells that invade other tissues. "Firstly, we determined the expression level of LRRC41 between paracancerous samples and cancer tissues according to the TCGA database." (PMID 34124163, 2021).
tumor (4 papers, 2021 to 2025). "According to the results of single-cell transcriptome sequencing data analysis, we observed that the expression value of LRRC41 is more in tumor tissues than paracancerous tissues." (PMID 34124163, 2021). "By using qRT-PCR, we compared the expression level of LRRC41 between two different tumor cell lines and normal liver cell line." (PMID 34124163, 2021). "Next, we analyzed the correlation between the LRRC41 expression level and ICB key genes’ expression levels adjusted by tumor purity by TIMER to explore the potential role of LRRC41 in ICB treatment." (PMID 34124163, 2021). "Compared with normal samples, the expression level of LRRC41 was higher in tumor samples." (PMID 34124163, 2021). "Additionally, IHC scores revealed higher levels of LRRC41 in tumor tissues." (PMID 38192337, 2023). "The results of immune cell infiltration presented higher subpopulations of immune cells (i.e., CD8+ T cells) and active immunological signature (i.e., APC costimulation) in hypomethylation of LRRC41, indicating LRRC41 hypomethylation might contribute to anti-tumor immune response." (PMID 34124163, 2021). "And LRRC41 is mainly expressed in Mast-c1-IL7R cells and Mast-c2-CPA3 cells in HCC tumor tissues." (PMID 34124163, 2021). "The biomarkers (RNASeq-derived) LRRC41, UBA2, and WDR77 are more expressed in IDHmut-non-codel compared to IDHwt, suggesting that such molecules can be part of the tumor development through transcriptional enhancing mechanisms." (PMID 41300918, 2025).